BCR (BCR activator of RhoGEF and GTPase)
Diseases named in the same sentence as BCR in open-access papers (continued):
Sharing a sentence is not in itself a finding about the gene and the disease.
gastrointestinal stromal tumor (16 papers, 2012 to 2026). "PDGFR dysregulation contributes to multiple malignancies, including gastrointestinal stromal tumors (GIST), chronic myeloid leukemia (with BCR-ABL fusion activating PDGFR-associated pathways), and various solid tumors." (PMID 41562694, 2026). "Beyond BCR::ABL1 mutations, genetic alterations have been critically evaluated for their role in conferring Imatinib resistance, especially in cancers like gastrointestinal stromal tumors (GISTs), where mutations in the KIT or PDGFRA genes are prevalent." (PMID 38607055, 2024). "Imatinib, for example, which has led to a significant increase in CML survival rates by selectively targeting the tumor-specific protein BCR/ABL, was included for the treatment of gastrointestinal stromal tumors (GIST), which are characterized by KIT-activating mutations." (PMID 36839989, 2023). "Another example of a successful cancer drug is Imatinib (Glivec) which targets BCR–ABL and platelet-derived growth factor receptor PDGFR tyrosine kinases which are driving hematopoietic malignancies and gastrointestinal stromal tumors." (PMID 35625561, 2022). "Imatinib, which was developed to target BCR-ABL, platelet-derived growth factor receptor (PDGFR), and c-Kit, is currently used to treat chronic myeloid leukemia, acute lymphoid leukemia, gastrointestinal stromal tumor (GIST), and hypereosinophilic syndrome." (PMID 35216379, 2022). "The TKIs designed to compete for the ATP binding site of the BCR-ABL fusion protein have been shown to be useful in not only CML but also a variety of other cancers including some non-small-cell lung carcinomas (NSCLC), renal cell carcinomas (RCC), and gastrointestinal stromal tumors (GIST)." (PMID 38646295, 2024).
Splenomegaly (16 papers, 2013 to 2026). Abnormal increased size of the spleen. "We demonstrate that MC deficiency prevents BCR::ABL1 induced splenomegaly and elevation of pro-inflammatory cytokines." (PMID 37161070, 2023). "Importantly, we demonstrate that genetic mast cell deficiency conferred by the Cpa3Cre allele prevents BCR::ABL1 induced splenomegaly and impairs the production of pro-inflammatory cytokines." (PMID 37161070, 2023). "These factors included male, late diagnosis, advanced performance status, the presence of splenomegaly, high-ELTS risk groups, a BCR::ABL1 domain mutation, and complete hematologic response after more than 30 days." (PMID 39698378, 2024). "We arrived at a JMML diagnosis after observing leukocytosis, less than 20% blast cells in the peripheral blood and bone marrow, increased monocyte counts, negativity for the BCR-ABL fusion gene, positivity for somatic KRAS mutation, and massive splenomegaly." (PMID 33327329, 2020). "The median expression was 0.31 (range: 0.08-1.37) in relation to the ABL gene, with a higher frequency of expression in CML patients presenting with splenomegaly (p<0.001), high Sokal score (p<0.001), and BCR-ABL expression from the first round (p=0.004)." (PMID 24385825, 2013). "Remarkably, and in contrast to the retroviral model, BCR::ABL1-positive MC-deficient mice showed no signs of splenomegaly." (PMID 37161070, 2023). "However, there was not a relationship found between the presence of JAK2 mutation and splenomegaly in cases with BCR‐ABL negative CMDs in a study from Turkey." (PMID 29732039, 2018). "We identified 39 individuals (0.019%) with two or more supporting reads of BCR::ABL1 or ABL1::BCR, most of whom had a diagnosis of CML, haematological features suspicious of CML (for example, splenomegaly or basophilia) or unspecified haematological issues." (PMID 40205062, 2025). "As expected, BCR/ABL expression following doxycycline withdrawal results in accumulation of myeloid progenitors and mature granulocytes in the bone marrow, spleen and peripheral blood and splenomegaly, within in one month." (PMID 31534508, 2019). "Similarly, splenomegaly was most common in SIL::TAL1 patients (100%), followed by E2A::PBX1 (75%), BCR::ABL (60%), MLL::AF4 (33.3%), TEL::AML1 (30%), negative (29.7%) and unknown (25.6%)." (PMID 41234729, 2025).
lupus (15 papers, 2008 to 2025). "In contrast, treatment with the same scFv A1 antibody resulted in BCR recognition on the surface of anti-C1q-specific B-cells and had a disease progression effect, enhancing lupus symptoms in the MRL/lpr mouse model of SLE." (PMID 40806179, 2025). "This is illustrated by the overexpression of CD79a and CD79b, molecules involved in the transduction of BCR signal, and of CD81 whose co-expression with BAFFR and CD38 in transitional B-cells is associated with active systemic lupus erythematosus." (PMID 39185406, 2024). "Increased SYK phosphorylation after BCR cross‐linking was found in peripheral blood B cells of patients with active systemic lupus erythematosus (SLE)." (PMID 37506139, 2023). "The ability of human CR1 to reduce autoimmunity has also been proven in humanized SCID mice transferred with PBMCs of lupus patients where cross-linking of the BCR and CR1 restored B cell tolerance and lowered the number of IgG anti-DNA producing plasma cells." (PMID 27981054, 2016). "However, when the 2-12H transgenic BCR was expressed on the lupus-prone MRL/lpr strain, apoptosis normalized and anti-Smith Ab secretion was restored and was linked with increased expression of the prosurvival receptor, BCMA, which binds BAFF and APRIL, relative to nonautoimmune mice." (PMID 37261716, 2023). "As in lupus, high abundance of IFN-α and pDC leads to BCR response, B cell proliferation, and antibody production and subsequent proteinuria in lupus." (PMID 29403161, 2017). "Likewise, cross-linking of BCR and CR1 was proven to lower the number of IgG anti-DNA producing plasma cells of lupus patients." (PMID 27981054, 2016). "However, activating TLR7 by CL095 together with co-activation of BCR can promote IL6 production by B cells, especially in B cells from lupus-prone mice." (PMID 26068236, 2015). "This is highly relevant to the report by Marshak-Rothstein and colleagues who had shown that co-engagement of BCR and TLR-9 by complexes of anti-DNA antibody and DNA may provide a mechanism for stimulation of autoreactive B cells in lupus." (PMID 18625057, 2008). "Therapy with the scFv A1 antibody resulted in BCR recognition on the surface of anti-C1q-specific B-cells and had a disease progression effect, enhancing lupus symptoms in the MRL/lpr mouse model of SLE." (PMID 40806179, 2025). "Since in AM14 B cells, INH-ODNs fail to inhibit signaling through the BCR, or by LPS, we concluded that the increased potency of Class R INH-ODNs for BCR/TLR9 coactivated autoreactive B cells could be advantageous for selective targeting of autoimmune B cells in lupus." (PMID 20490286, 2010). "In the mouse model of lupus (AM14 B cells), the BCR has RF activity and its stimulation fails to promote B cell activation (anergy) but TLR9 engagement leads to B cell activation and proliferation." (PMID 26649443, 2015). "Additionally, we used only one lupus mouse model and did not include TCR and BCR diversity sequencing." (PMID 40728997, 2025).
multiple myeloma (14 papers, 2013 to 2025). "We examined BCR rearrangement in UPNs 14–17: UPNs15 and 16 had plasma cell myeloma and a small CD5+ B cell clone, respectively." (PMID 37586319, 2023). "The BTK inhibitor Ibr is already approved for the treatment of CLL and mantle cell lymphoma and was further effective in pre-clinical AML studies, multiple myeloma, and pre-BCR B-ALL." (PMID 32684632, 2020). "Furthermore, N-glycosylation of the clonotypic BcR IG has also been reported, albeit less frequently, in plasma cell disorders and B cell malignancies, such as AL amyloidosis." (PMID 36845709, 2023). "As the DG75 Burkitt’s lymphoma cell line not only expresses a membrane-anchored BCR but also secretes soluble Ig, we evaluated the serum levels of the scFull-Ig as a biomarker of the tumor mass, similar to the serum monoclonal Ig components paralleling tumor growth in myeloma patients." (PMID 41438137, 2025). "The BCR-ABL fusion gene is involved in the Philadelphia chromosome of CML, but it is rarely reported in myelomas." (PMID 35342415, 2022). "The majority of these studies have focussed on solid tumors, however there are reports in haematological malignancies including multiple myeloma and T-ALL, and we have previously reported a role for SphK2 in B lineage ALL using a BCR/ABL1-dependent model." (PMID 29441205, 2018). "Moreover, examination of the bone marrow showed a 19% population of myeloma cells and an overall 97% positivity for BCR-ABL fusion signal, indicating that some of the myeloma cells were positive for BCR-ABL rearrangement." (PMID 25386371, 2014). "Notably, no external validation studies were found for multiple myeloma therapies, and validation for patients treated with BCR-ABL or VEGF inhibitors was each limited to a single study." (PMID 40987514, 2025).
Burkitt lymphoma (13 papers, 2014 to 2025). A rare form of malignant mature B-cell non-Hodgkin lymphoma. "Burkitt lymphoma survival is dependent on “tonic” BCR signaling, which activates the PI3K pathway in BL cells, and the consequent signaling cascade promotes proliferation." (PMID 34283060, 2021). "To test the importance of these adaptors, we used pull‐down assays to analyze interactions of endophilin A2‐GFP with the BCR in DG75 Burkitt lymphoma cells in the context of GRB2 or BLNK deletion." (PMID 34323351, 2021). "Our study links MYC to BCR signaling in Burkitt lymphoma through up regulation of SYK transcription by MYC and GCN5." (PMID 31645904, 2019). "Overall, GCN5 HAT inhibition disrupts BCR signaling and reduces phosphorylation of key effectors, thereby reducing viability and inducing apoptosis in Burkitt lymphoma cells." (PMID 31645904, 2019). "Burkitt lymphoma survival is dependent on “tonic” BCR signaling." (PMID 31645904, 2019). "Similarly, this globoside has also been shown to regulate downstream BCR signaling in Burkitt lymphoma (BL) cells by activating Lyn and Syk kinases, suggesting that it is also involved in BCR-mediated apoptosis regulation." (PMID 35565181, 2022).
eosinophilia (13 papers, 2013 to 2026). "In contrast, BCR::ABL1 or tyrosine kinase fusions associated with myeloid/lymphoid neoplasms with eosinophilia, as well as JAK2, MPL, and CALR mutations, are used as exclusion criteria." (PMID 38992589, 2024). "After ruling out the hypothesis of non−hematologic origin, testing for gene rearrangements associated with clonal eosinophilia, such as BCR::ABL1, PDGFRA, PDGFRB, FGFR1, PCM1::JAK2, and JAK2::V617F, did not yield any definitive clues." (PMID 38992589, 2024). "While basophilia and eosinophilia, particularly in combination, are more typical for BCR::ABL1pos CML, elevated hemoglobin/hematocrit and the presence of normoblasts in PB are more typical for JAK2 V617Fpos MPN." (PMID 40681596, 2025). "In a case series where 22 patients diagnosed with myeloid/lymphoid neoplasm associated with eosinophilia and FGFR1 rearrangements were treated with allogeneic hematopoietic stem cell transplantation, 7 of them had BCR::FGFR1 rearrangement." (PMID 36698221, 2023). "We present the case of a male adult patient diagnosed with myeloid/lymphoid neoplasm with eosinophilia and BCR::FGFR1 rearrangement with transformation to cortical T-lymphoblastic lymphoma and erythroid precursors." (PMID 36698221, 2023). "BCR::ABL1 is found in 95% of CML, in which leukocytosis with granulocytic precursors, eosinophilia and basophilia are the most preponderant abnormalities on the hemogram." (PMID 36980287, 2023). "In a next-generation sequencing study, BCR::FGFR1 rearrangement was documented, a diagnosis of myeloid/lymphoid neoplasia with eosinophilia and BCR::FGFR1 rearrangement was made, and hydroxyurea therapy was initiated." (PMID 36698221, 2023). "Eosinophilia workup was done to rule out the common causes, including LDH, IgE, ova and parasite, BCR/ABL mutation, and JAK2 mutation, and they all returned negative." (PMID 41477390, 2025). "Unlike other rearrangements of PDGFRA, the clinical manifestations of BCR-PDGFRA rearrangement are resembling CML without eosinophilia increase." (PMID 35713428, 2022). "Eosinophilia and thrombocytosis workup was performed to exclude other reasons, and it was unremarkable, including lactate dehydrogenase (LDH), immunoglobulin E (IgE) level, BCR/ABL (breakpoint cluster region, Abelson murine leukemia), JAK2 tyrosine-protein kinase mutation, ova, and parasite." (PMID 41477390, 2025). "Therefore, an RNA-based study capable of sensitively detecting ETV6::ABL1 should be used for diagnostic evaluation, especially in patients with MPN featuring eosinophilia and lacking the BCR::ABL1, considering clonal burden and disease phenotype in the interpretation of results." (PMID 39066837, 2024).
influenza (13 papers, 2013 to 2025). An acute viral infection of the respiratory tract, occurring in isolated cases, in epidemics, or in pandemics; it is caused by serologically different strains of viruses (influenzaviruses) designated A, B, and C, has a 3-day incubation period, and usually lasts for 3 to 10 days. "We further applied the fine-tuned models to BCR repertoire data for influenza and SARS-CoV-2 vaccination to investigate their ability to capture changes for vaccination response." (PMID 40163503, 2025). "Stimulation with the influenza vaccine or BCR-independent stimulation with CpG increased the frequency of plasmablasts compared to the unstimulated conditions." (PMID 39355250, 2024). "Public influenza-specific BCR CDR3 amino acid sequences have been reported in humans, although many of these appear to arise from convergent selection rather than identical nucleotide sequences in different individuals." (PMID 39534604, 2024). "We further applied the fine-tuned models to BCR repertoire data for influenza and SARS-CoV-2 vaccination to investigate their ability to capture changes induced by ongoing immune responses." (PMID 38798340, 2024). "Based upon recovered BCR sequences from GC-resident B cells, we find GC in the lung maintain a capacity to drive maturation of the influenza-specific B cell response, with the continued accumulation of somatic mutations observed over 56 days post-infection." (PMID 30984186, 2019). "In work co-submitted with this manuscript, Savage and colleagues show that TLR activation of B-1a cells both in vitro and in the context of influenza infection results in the loss of surface CD5 and a concomitant increase in BCR-downstream signaling." (PMID 31433298, 2019). "Based on these results, we concluded that blocking BCR-independent binding sites with mismatched influenza subunit antigens increases the specificity of identifying H1+ B-cells and decided to utilize this staining approach in the subsequent experiments." (PMID 23976947, 2013). "Furthermore, we apply the supervised fine-tuned models to BCR repertoire data related to influenza and SARS-CoV-2 vaccination, demonstrating their ability to capture changes in repertoire following vaccination." (PMID 40163503, 2025). "Application of the supervised fine-tuned models to BCR repertoire data demonstrated that these models could recognize the specific responses elicited by influenza and SARS-CoV-2 vaccination." (PMID 38798340, 2024). "We used the same criterion to process the influenza vaccination repertoire datasets, which consisted of six influenza vaccine-responsive donors with peripheral blood samples taken at pre-vaccination (Day 0) and seven days post-vaccination (Day 7) for paired BCR heavy and light chain sequencing." (PMID 38798340, 2024). "Our data here shows that IgD+ABC are the progenitors of a predominant aged B cell response against influenza infection, suggests that IgD+ABC express a broad BCR repertoire that includes a cohort that recognizes influenza and can respond to infection in aged mice." (PMID 36056604, 2022). "Furthermore, we applied the fine-tuned classifiers to longitudinal paired BCR repertoire data related to influenza and SARS-CoV-2 vaccination, showing their ability to capture changes in repertoire following vaccination, as evidenced by shifts in predicted binding probabilities." (PMID 38798340, 2024). "Our findings demonstrate that B-cells carrying immunglobulin receptors specific for type A or B influenza HA can be identified in ex vivo PBMCs by using fluorochrome-tagged rHA as antigenic baits and unlabeled mismatched mono-bulk vaccine subunit antigens to block BCR-independent binding." (PMID 23976947, 2013). "To further evaluate if the fine-tuned language model classifiers capture specificity information, we applied the classifiers to two single-cell BCR repertoire datasets measuring immune response to SARS-CoV-2 vaccination and influenza vaccination." (PMID 38798340, 2024).
influenza (continued). "For dataset 3 (human, BCR, baseline versus influenza vaccination), we found that profiles did not cluster by immunological status." (PMID 26140055, 2015). "Indeed, we found diversity profile intersection for all of the BCR and TCR datasets within and across immunological status, which were as varied as healthy, cancer (CLL), influenza vaccination and transplantation." (PMID 26140055, 2015).
chronic neutrophilic leukemia (12 papers, 2022 to 2025). A rare chronic myeloproliferative neoplasm characterized by neutrophilic leukocytosis. "Its differential diagnosis includes BCR::ABL1 negative CML and other MPNs such as chronic neutrophilic leukemia (CNL) and chronic eosinophilic leukemia." (PMID 38992589, 2024).
mantle cell lymphoma (12 papers, 2015 to 2025). Mantle cell lymphoma is a rare form of malignant non-Hodgkin lymphoma affecting B lymphocytes in the lymph nodes in a region called the ``mantle zone''. "For example, BTK lies within the pathway controlling α4β1-mediated adhesion in BCR-stimulated cells and can also mediate chemokine-induced migration and homing of normal B, mantle-cell lymphoma and CLL cells." (PMID 25632006, 2015). "In mantle cell lymphoma (MCL), resistance to ibrutinib (the BCR antagonist that targets Bruton’s tyrosine kinase) is characterised by aberrant non-canonical NF-kB signalling due to mutations in TRAF2 and BIRC3." (PMID 37835430, 2023). "Mantle cell lymphoma (MCL) is a largely incurable B‐cell malignancy that heavily relies on B‐cell receptor (BCR) signaling for survival and propagation." (PMID 36214609, 2022). "The MCL (Mantle cell lymphoma) and CLL (chronic lymphocytic leukemia) have both been treated with the BTK inhibitors, by inhibiting BCR signaling and controlling innate or adaptive immunity." (PMID 39898116, 2025).
primary myelofibrosis (12 papers, 2013 to 2026). Myelofibrosis with myeloid metaplasia is a myeloproliferative disease with annual incidence of approximately 1 case per 100,000 individuals and age at diagnosis around 60 (an increased prevalence is noted in Ashkenazi Jews). "PMF and post-ET/PV MF are the BCR::ABL1-neg MPNs categories with the worst survival rates in adults and can only be cured by allo-HSCT, which can induce molecular remission and resolution of bone marrow fibrosis." (PMID 38627449, 2024).